L1CAM (L1 cell adhesion molecule)
Diseases named in the same sentence as L1CAM in open-access papers (continued):
Sharing a sentence is not in itself a finding about the gene and the disease.
glioma (64 papers, 2008 to 2025). A benign or malignant brain and spinal cord tumor that arises from glial cells (astrocytes, oligodendrocytes, ependymal cells). "Cell adhesion molecule L1CAM is expressed in high-grade gliomas and is widely associated with tumor cell migration, invasion, and resistance to apoptosis." (PMID 39598347, 2024). "L1 cell adhesion molecule (L1cam) is a neural adhesion molecule whose levels have been shown to associate with glioblastoma, and its knockdown can suppress glioma stem cell growth." (PMID 36497269, 2022). "The transient receptor potential melastatin family member 8 (TRPM8), bone morphogenetic protein 2 (BMP2) and L1CAM are upregulated in GBMs compared to normal brain tissue and are associated with glioma cell proliferation, migration and invasion." (PMID 34910361, 2022). "Further analysis demonstrated that L1CAM strong positive expression was significantly associated with poor prognosis in gliomas, both in our cohort (p < 0.001) and TCGA (p < 0.009) dataset." (PMID 32509846, 2020). "Increased levels of L1CAM-ECD are caused by an upregulation of ADAM 10 in glioma, ovarian cancer and colon and cancer cells, and shedding is promoted by the presence of serum or HGF, hypoxia or apoptotic stimuli." (PMID 31455004, 2019). "In vitro treatment of CD133+ glioma cells with L1CAM-shRNA expressing lentiviruses causes reduced neurosphere formation and size and increased apoptosis while having little impact on CD133- cells." (PMID 24212632, 2011). "Herein, we report that L1CAM might be a critical regulator of VM formation in glioma, and might be associated with the resistance of glioma to antiangiogenic therapy." (PMID 36708044, 2023). "Next, we aimed to elucidate the mechanism underlying L1CAM-controlled tumor progression in glioma." (PMID 35473609, 2022). "In glioma, shutting down of L1CAM expression causes complete cessation of cellular migration." (PMID 35473609, 2022). "Moreover, clinical data analysis demonstrated that L1CAM expression was a risk factor for glioma patients, with higher values pertaining to a poor prognosis." (PMID 35473609, 2022). "Among all the 109 L1CAM positive gliomas, 44 cases were IDH mutated (10 astrocytomas, 10 oligodendrogliomas, 8 anaplastic astrocytomas, 10 anaplastic oligodendrogliomas, and 6 GBMs) and 65 cases were IDH wild-type (16 astrocytomas, 10 anaplastic astrocytomas, and 39 GBMs)." (PMID 32509846, 2020). "Inhibition of GSK3 led to reduced expression of cell adhesion molecule L1CAM, which is overexpressed both in IDHmut glioma and in our model system (CGGA)." (PMID 40307935, 2025). "L1CAM is likely to help maintain stemness of glioma, colorectal cancer, and ovarian cancer stem cells." (PMID 39201435, 2024). "In another study, researchers isolated tumor cell sEVs packaging L1CAM and found these sEVs promoted glioma cell migration and proliferation." (PMID 38951882, 2024). "L1CAM is overexpressed in glioma stem cells and is an important factor in maintaining the growth and survival of glioma stem cells." (PMID 37015905, 2023). "The first is to convert the apoptosis‐related factor ligand (FasL) in astrocytes into the paracrine death signal pathway of cancer cells, or effect by inhibiting the axon Pathfinder L1 cell adhesion molecule (L1CAM) to promote the growth of glioma." (PMID 35961680, 2023). "L1 cell adhesion molecule (L1CAM) was shown to enhance the radiation resistance of glioma stem cells by increasing the phosphorylation of ATM and CHK2, slowing down cell death, and improving the formation efficiency and size of GSC tumor spheres." (PMID 37700319, 2023). "Recently, it has been demonstrated by our team and others that the transmembrane glycoprotein L1CAM is overexpressed in multiple human malignancies brain metastases, glioma, non-small cell lung cancer, and colon cancer." (PMID 36387224, 2022).
glioma (continued). "Collectively, these results suggested that serotonin upregulated NF-κB expression through L1CAM signaling, thus resulting in tumor progression and a poor prognosis in glioma patients." (PMID 35473609, 2022). "Taken together, these data suggested that TPH-1 facilitated cellular proliferation, migration, and chemoresistance in glioma through the serotonin/L1CAM/NF-κB pathway." (PMID 35473609, 2022). "Our study further indicated that TPH-1 drove glioma development in an L1-cell adhesion molecule (L1-CAM)/NF-κB dependent manner." (PMID 35473609, 2022). "Taken together, these results suggested that serotonin facilitated glioma development by regulating L1CAM expression." (PMID 35473609, 2022). "It has been shown that increased levels of soluble L1CAM ectodomain are induced by an upregulation of ADAM10 in glioma, ovarian cancer, and colon cancer." (PMID 34228897, 2022). "THP1 overexpression and serotonin treatment resulted in the upregulation of L1CAM in LN229 and T98G cells, which suggested a direct relationship between serotonin production and L1CAM signaling in glioma." (PMID 35473609, 2022). "Consistently, the suppressive effects were also observed in cellular apoptosis analysis, suggesting that L1CAM played a role in glioma development." (PMID 35473609, 2022). "In conclusion, we demonstrated that TPH-1 functioned through the serotonin/L1CAM/NF-κB pathway, thus facilitating glioma cell proliferation, migration, and chemoresistance." (PMID 35473609, 2022). "For instance, LGALS3, L1CAM, and SCAMP3 were associated with the shorten OS of glioma patients by promoting the proliferation or other malignant tumor characteristics of glioma." (PMID 33750478, 2021). "In our study, L1CAM was found to be a significant poor prognosis in glioma, and it was an independent prognostic factor in multivariate Cox analysis, indicating its prognostic importance in glioma." (PMID 32509846, 2020). "L1CAM was positive in 109 cases (19.29%) of all 565 glioma cases, with 18.27% in low-grade gliomas and 19.84% in high-grade gliomas, respectively." (PMID 32509846, 2020). "Intriguingly, L1CAM was also found in glioma stem cells; Bao showed that L1CAM was overexpressed in CD133+ glioblastoma cells." (PMID 32509846, 2020). "In gliomas, L1CAM is overexpressed and plays a role in tumor invasion, and is necessary for survival and growth of CD133+ cells with stem like properties." (PMID 32722427, 2020). "Out of 565 glioma cases in our cohort, 109 (19%) tumors were found to be L1CAM highly positive, with 36 highly positive cases (18.27%) in low-grade glioma and 73 highly positive cases (19.84%) in high-grade gliomas, respectively." (PMID 32509846, 2020). "Anderson suggested that inhibitors of FGFR have the potential to decrease the aggressiveness of high-grade gliomas expressing L1CAM." (PMID 32509846, 2020). "In order to find its correlation with C11orf95-RELA fusion in other types of gliomas, we selected all the L1CAM IHC highly positive cases to do the FISH test using RELA break-apart probes." (PMID 32509846, 2020). "In stratification analysis, L1CAM was also a significant poor prognostic marker both in low-grade glioma (WHO I and II) and high-grade glioma (WHO III and IV)." (PMID 32509846, 2020). "Mohanan further confirmed L1CAM stimulated high-grade glioma cell motility and proliferation through the fibroblast growth factor receptor (FGFR)." (PMID 32509846, 2020). "Although uncorrelated with C11orf95-RELA fusion, L1CAM was a significant poor prognostic marker in glioma patients." (PMID 32509846, 2020). "Intriguingly, we also detected the strong expression of L1CAM protein in some glioma tissues in HPA, with 2 of 12 (16.67%) glioma patients show high expression of L1CAM." (PMID 32509846, 2020). "Several cell adhesion molecules have been identified to underlie the occurrence of malignancies in gliomas, including adhesion molecule on glia (AMOG) and neural cell adhesion molecule L1 (L1CAM, hereafter abbreviated L1)." (PMID 31510944, 2019).
glioma (continued). "Roles of the adhesion molecules on glia (AMOG) and L1CAM (L1) in glioma cells have been shown to correlate with tumorigenesis: Increased expression of L1 and decreased expression of AMOG correlate with degree of malignancy." (PMID 31510944, 2019). "Glioma EVs containing immunoglobulin superfamily protein L1CAM were shown to promote cell motility, proliferation and invasiveness in glioma cells in vitro." (PMID 32038644, 2019). "In both glioma and ovarian cancer exosomal L1CAM contributes to migration through similar mechanisms as their corresponding non-exosomal counterparts, through integrin interaction and subsequent FAK or ERK phosphorylation." (PMID 31455004, 2019). "The full-length neural adhesion/recognition protein L1 (L1CAM) is presented in exosomes produced by glioma cells." (PMID 29642503, 2018). "A disintegrin and metalloproteinase domain-containing protein 10 (ADAM10), the matrix proteinase increases consistently with glioma grade, catalyzes proteolysis of L1CAM and releases the ectodomain of L1CAM." (PMID 29642503, 2018). "L1CAM knockdown in CD133+ glioma cells prior to xenotransplantation into immunodeficient mice markedly inhibited in vivo tumorigenesis and prolonged survival of the xenograft recipients." (PMID 26880988, 2016). "In gliomas, L1CAM-positive and CD133-positive cells cosegregate, and levels of L1CAM are higher in glioma cells expressing CD133 than in normal neural progenitors." (PMID 22685459, 2012). "In cancers, it is overexpressed in gliomas, in which it plays a role in tumor invasion and other solid tumors, including colorectal cancer where L1CAM functions as a prognostic indicator." (PMID 22685459, 2012). "While there is controversy surrounding CD133 as a CSC marker, many proposed glioma CSC markers (including L1CAM, A2B5, and integrin alpha 6) overlap with CD133." (PMID 21961046, 2011). "In vivo studies using L1CAM-shRNA have shown that mice bearing glioma xenografts with decreased L1CAM expression survived nearly twice as long as those bearing tumors with wild type L1CAM expression." (PMID 24212632, 2011). "Our lab has found that attenuating L1CAM by this method in glioma cells decreased focal complex turnover, reduced cell motility in vitro, and halted brain invasiveness in vivo." (PMID 20840789, 2010). "But recent studies unveiled L1CAM's abnormal presence in glioma, melanoma, ovarian, colon and pancreatic cancers." (PMID 20840789, 2010). "L1CAM has been shown to be involved in C6 rat glioma cell migration via its imunoglobulin C2-like domain, however, the expression of L1CAM is lower in glioma when compared to a neuroblastoma cell line." (PMID 20419098, 2010). "This confirmed that gliomas with 1p19q codeletion overexpressed neuronal/normal brain genes (AKR1C3, C20orf42, CTTNBP2, L1CAM, GALNT13) as well as genes implicated in gliogenesis and neurogenesis (OLIG2, BMP2, NOG, DCX, ATOH8)." (PMID 18492260, 2008). "The transmembrane glycoprotein L1CAM drives migration and invasion in gliomas." (PMID 41304780, 2025). "Expression of LGG-related marker L1CAM was affected by perturbation of all pathways, though only modulation of WNT/GSK3-signaling resulted in profound molecular transformation, including glioma-associated genes and programs regulating cellular architecture and cell replication." (PMID 40307935, 2025). "Some regulators of MRM were associated with the expression of NCAM1, NCAM2, and L1CAM, which indicated that MRM may facilitate glioma development via astrocytic modulation." (PMID 38824202, 2024). "Together, our findings demonstrated a critical role of L1CAM in regulating VM formation in glioma, and that L1CAM might be a potential target for ameliorating tumor resistance to antiangiogenic therapy in glioma patients." (PMID 36708044, 2023). "Moreover, we identified that activation of the downstream PI3K/AKT signaling pathway of the L1CAM/HK2 cascade is critical for VM formation by glioma cells." (PMID 36708044, 2023).
glioma (continued). "Meanwhile, Yang has confirmed that tryptophan metabolic enzyme tryptophan hydro xylase 1 could promote glioma progression through serotonin/L1CAM/NF-κB signaling pathway." (PMID 36927689, 2023). "Besides, L1CAM depletion suppressed tumor growth of glioma, neuroblastoma and ovarian carcinoma and prostate cancer cells in mice, while L1CAM overexpression correlates with progression of these tumor entities." (PMID 34228897, 2022). "Notably, an increased mRNA expression of L1CAM was observed in the TPH-1 high glioma cancer tissues, and L1CAM reportedly serves as an L1 cell adhesion molecule, thereby participating in the process of cellular migration of tumor cells." (PMID 35473609, 2022). "Furthermore, we observed that L1CAM expression was positively correlated with a poor prognosis of glioma patients." (PMID 35473609, 2022). "Importantly, we have highlighted the involvement of L1CAM in TPH-1 mediated glioma progression, as indicated by the upregulation of L1CAM in THP1 overexpressing glioma cells." (PMID 35473609, 2022). "L1CAM is a well-established neural cell adhesion molecule that was reported to drive cancer stem cell self-renewal potential, tumor survival, and evasion of apoptosis in gliomas." (PMID 34422720, 2021). "However, limited articles researched the prognosis significance of L1CAM in glioma, except ependymoma." (PMID 32509846, 2020). "However, only few studies researched L1CAM in glioma, it found to act as a putative role in the histogenesis of glioma, which conferred chemoresistance and stimulated glioma cell motility and proliferation." (PMID 32509846, 2020). "More aggressive treatment should be taken for these patients and L1CAM might be a promising therapeutic target in glioma." (PMID 32509846, 2020). "It seemed L1CAM acted different molecular signals in glioma compared with other solid cancers." (PMID 32509846, 2020). "Furthermore, our RNA‐sequencing data demonstrated that 3 of the genes (SCN5A, L1CAM, BMP2) affected with the anti‐ELTD1 treatment that were directly associated with gliomas influenced and interacted with Notch signalling." (PMID 31863639, 2020). "Additionally, targeting L1CAM with lentiviral-mediated shRNA interference in CD133+ glioma cells inhibited GSC growth and neurosphere formation, and induced GSC apoptosis." (PMID 32722427, 2020). "We examined the expression of L1CAM in 565 glioma cases (WHO grade I-IV)." (PMID 32509846, 2020). "Three studies focused on the impact of exosomal L1CAM forms in glioma and ovarian cancer which potentially include LICAM-FL associated with exosomes (Exo-FL) or L1-CAM lacking either the cytoplasmic or the N-terminal domain (Exo-ΔCT and Exo-ΔNT, respectively) on tumor progression." (PMID 31455004, 2019). "In glioma, L1CAM-ECD promotes cell migration and proliferation by a mechanism that depends on αvβ3 and αvβ5 integrins and FAK, and on FGFR1 activity, suggesting that the L1CAM-ECD mediates its effect by heterophilic interactions of both integrins and the FGFR1 in these tumors." (PMID 31455004, 2019). "Furthermore, the L1-CAM/FGFR1/Anosmin-1 complex regulates neurite branching and L1-CAM-mediated FGFR1 transactivation induces glioma cell proliferation and motility." (PMID 31337028, 2019). "Furthermore, intracranial administration of lentiviral shRNAs against L1CAM in glioma xenografts also substantially suppressed tumor growth and prolonged survival of the tumor-bearing mice." (PMID 26880988, 2016). "Finally, in many tumors, including gliomas and glioblastomas, L1CAM does support proliferation and invasiveness, and is thus envisaged as a biomarker of poor prognosis and a target of specific anti-tumor therapy." (PMID 22973895, 2013). "Indeed, L1CAM-mediated signaling confers radioresistance in glioma stem cells by enhancing Mre11, Rad50, and Nbs1 (MRN) complex function through Myc-NBS1-ATM axis and leading to DNA checkpoint activation and DNA repair." (PMID 22685459, 2012).
glioma (continued). "Studies from other research groups and ours have shown that in colon cancer and glioma models, L1CAM expression and proteolysis can be detected at the invasive front of cell cultures, indicating the role of L1 shedding in the pioneering stage of cancer cell migration." (PMID 20840789, 2010). "L1CAM was found to be a significant marker in predicting the prognosis of glioma patients, and may be a promising therapeutic target and monitoring index in glioma patients." (PMID 38279111, 2024). "The authors identified L1CAM as a crucial regulatory factor for modulating vasculogenic mimicry formation in glioma, which might be a potential target for ameliorating tumor resistance to antiangiogenic therapy in glioma patients." (PMID 36708044, 2023). "In addition, the results indicated that miR‐143‐3p, which might directly target the 3'UTR of the hexokinase 2 (HK2) gene to regulate its protein expression, was subsequently involved in L1CAM‐mediated VM formation by glioma cells." (PMID 36708044, 2023). "Therefore, we sought to examine the role of L1CAM in regulating glioma development." (PMID 35473609, 2022). "It was suggested that L1CAM might also be a promising individualized therapeutic target in glioma." (PMID 32509846, 2020). "However, the L1CAM protein expression in large sample gliomas other than ependymoma, its relationship with the RELA gene and its prognostic significance remained unknown." (PMID 32509846, 2020). "Since SCLC tissues expressed L1CAM mRNA to a greater extent than adjacent normal tissues, it is likely to act as an oncogene in SCLC like glioma or gynecological cancer." (PMID 39201435, 2024). "L1-cell adhesion molecule (L1CAM), the autocrine/paracrine of which is one of the factors that promote glioma cell proliferation, migration, and invasiveness." (PMID 38951882, 2024). "In contrast, p75NTR gene knockdown stimulates the expression of HIF-1α, fibronectin, and L1CAM, and the phosphorylation of Src, focal adhesion kinase (FAK), and paxillin, which increase the migration of C6 glioma cells." (PMID 35956937, 2022). "In addition, L1CAM may be a promising therapeutic target and monitoring index in glioma patients." (PMID 32509846, 2020). "Currently recognised specific markers for human glioma stem cells (HuGSCs) include CD133, integrin α6, CD171 (L1CAM), CD15, nestin, and CD44 1, 5-7." (PMID 32174801, 2020). "In addition, the previous researches had also shown cytokine neuregulin 1 (Nrg1) could upregulate the L1CAM expression to enhancing the migration of glioma cells, and TGF-β1 could mediate L1CAM expression, then led to the downregulation of caspase-8 and apoptosis resistance." (PMID 32509846, 2020). "L1CAM knockdown decreased OLIG2 expression and upregulated the CDKN1 (also known as p21) tumor suppressor in CD133+ glioma cells." (PMID 32722427, 2020). "L1 cell adhesion molecule known as L1-CAM, is a well-established CSC marker in various tumors including gliomas and NB and has been shown to confer chemo- and radio-resistance in these aggressive cancers." (PMID 31191243, 2019). "Twelve studies investigated the effects of the cleaved, soluble N-terminal ectodomain of L1CAM (L1CAM-ECD) on tumor progression, mostly focusing on gliomas, ovarian cancer, and pancreatic cancer." (PMID 31455004, 2019). "One of the factors that increases glioma cell proliferation, motility, and invasiveness is autocrine/paracrine stimulation by cell adhesion molecule L1CAM (L1, CD171)." (PMID 31426278, 2019). "Research has shown that some stemness markers such as L1CAM (CD171), Bmi-1, SOX2, and CD44 can also regulate glioma radioresistance." (PMID 29246031, 2017). "Mechanistically, L1CAM knockdown decreased the expression of bHLH transcription factor and upregulated p21WAF1/CIP1 tumor suppresser in CD133+ glioma cells." (PMID 26880988, 2016).